AKT2 (AKT serine/threonine kinase 2)
Diseases named in the same sentence as AKT2 in open-access papers (continued):
Sharing a sentence is not in itself a finding about the gene and the disease.
type 2 diabetes (26 papers, 2012 to 2025). "Total body Akt2 knockout mice develop severe type-2 diabetes, and cells deficient in Akt2 have impaired glucose utilisation." (PMID 25929188, 2015). "The role of AKT is implicated in human type 2 diabetes with the identification of a family with type 2 diabetes that had inherited loss of AKT2 missense mutation that seems to act in a dominant-negative manner to inhibit other AKT isoforms." (PMID 22680924, 2012). "For example, in different types of transgenic animal models of type II diabetes, Akt2 −/− insulin‐resistant mice and Goto‐Kakizaki rats showed decreased autophagy and increased autophagy, respectively." (PMID 38113341, 2024). "Akt2 null mice develop severe type 2 diabetes, suggesting a central role for Akt2 in the maintenance of glucose homeostasis." (PMID 36180910, 2022). "Variants in AKT2 and PTEN have been associated with type 2 diabetes risk; their presence reduces activity of the insulin signalling pathway, leading to reduced glucose uptake and insulin resistance in insulin-responsive tissues." (PMID 32705315, 2020). "Akt2 knockout mice develop a type 2 diabetes-like phenotype, and cells derived from those mice show impaired glucose utilization, suggesting a key role for Akt2 in the regulation of glucose homeostasis." (PMID 32309540, 2013). "By contrast, Akt2 null mice develop type 2 diabetes and impaired glucose utilization, suggesting that Akt2 function is more specific for the insulin receptor signaling pathway." (PMID 22481935, 2012). "Several type 2 diabetes susceptibility genes are known to play a role in cancer development (e.g. TCF7L2, CDKN2A/B, AKT2, PPARG, PTEN and HNF1B) but the evidence is relatively scarce for shared genetic aetiology between type 2 diabetes predisposing alleles and the observationally associated cancers." (PMID 32705315, 2020). "Akt2 is a critical mediator for normal cell growth and proliferation; however, aberrant regulation may lead to other diseases in addition to type 2 diabetes, such as cancer." (PMID 26465754, 2015). "Akt2 knockout mice develop a type 2 diabetes-like phenotype and therefore it has been speculated that Akt2 plays a central role in glucose homeostasis." (PMID 25811375, 2015). "An increased expression of Akt2 has likewise been found in healthy, elderly men and in obese middle‐aged men with or without type 2 diabetes following 8–10 weeks of endurance type exercise training." (PMID 34042297, 2021). "Therefore, we note that we identified differential methylation of single CpG sites within 7/59, two CpG sites in 2/59 (BCL11A, AKT2), and consistent changes in six CpG sites in 1/59 (KCNQ1) type-2 diabetes genes." (PMID 25651499, 2015).
neuroblastoma (23 papers, 2010 to 2024). Neuroblastoma (NB) is the most common solid, extracranial childhood tumor. "Though the Akt1/Akt2 ratio was found to regulate expression of miR-200 and miR-182 in a neuroblastoma cell line, and modulation of these miRNAs caused differential expression of EMT-related proteins, whether this is the case in hibernating TLGS remains inconclusive." (PMID 29440989, 2018). "We previously demonstrated that AKT2 plays critical roles in the regulation of neuroblastoma tumorigenesis." (PMID 31608140, 2019). "AKT2 has been proved as a target for miR-184 in neuroblastoma cell line, while their interaction in RPE cells remains inclusive." (PMID 27418134, 2016). "Subsequently, miR-184 was found to be involved in suppressing cell survival and growth by targeting AKT2 in neuroblastoma cells." (PMID 24976536, 2014). "We also confirmed that GRP-R is upstream of AKT2 and in turn, regulated N-myc expression via AKT2 in neuroblastoma cells." (PMID 23468863, 2013). "Xenografts established by injecting AKT2 silenced human neuroblastoma cells into murine spleen expressed decreased levels of AKT2 and resulted in fewer liver metastases compared to controls in vivo." (PMID 23468863, 2013). "Consistent with other cancer cell types, we report, for the first time, that AKT2 is critical for neuroblastoma progression." (PMID 23468863, 2013). "We also show a novel evidence that AKT2 negatively regulates Gli1 nuclear accumulation, thereby, affecting its function as a transcription modulator in neuroblastoma cells." (PMID 23900341, 2013). "We also demonstrated that AKT2 overexpression regulates the nuclear-cytoplasmic distribution of exogenous Gli1 protein in neuroblastoma cells by relieving a GSK3β-mediated destabilization of SUFU, a negative regulator of Gli1 nuclear translocation." (PMID 23900341, 2013). "Collectively, our findings suggest an important role of Gli1 as a tumor suppressor in neuroblastoma, and offer a mechanism by which AKT2 regulates the subcellular localization, and in turn, inhibits the tumor-suppressive function of Gli1 in neuroblastoma." (PMID 23900341, 2013). "Surprisingly, the AKT2 isoform negatively regulated Gli1 function in both neuroblastoma cell lines we tested." (PMID 23900341, 2013). "Taken together, these observations confirm that AKT2 is a critical regulator of N-myc expression in neuroblastoma cells." (PMID 23468863, 2013). "Our findings identify a potential novel role for AKT2 in the cytoplasmic retention of Gli1 in neuroblastoma cells." (PMID 23900341, 2013). "This is a novel observation, implicating a specific AKT2 isoform as a critical regulator of N-myc in neuroblastoma cells." (PMID 23468863, 2013). "A later study found that miR-184 was involved in a common genetic pathway through targeting the serine/threonine kinase AKT2 by acting with MYCN transcription factor to inhibit neuroblastoma cell survival." (PMID 23724109, 2013). "Taken together, our data confirms that AKT2 inhibits the tumor-suppressive role of Gli1 by suppressing its transcriptional activity in neuroblastoma cells." (PMID 23900341, 2013). "Here, we report a novel finding that of the three AKT isoforms, AKT2 specifically regulated N-myc expression in neuroblastoma cells." (PMID 23468863, 2013). "AKT2-mediated inhibition of Gli1 transcriptional activity suppressed the induction of Gli1 target genes involved in the differentiation of neuroblastoma cells." (PMID 23900341, 2013). "In this study, we identified a novel regulation of N-myc expression by the AKT2 isoform in neuroblastoma cells." (PMID 23468863, 2013). "Collectively, our data suggest an inhibitory role for the PI3K/AKT2 signaling on Gli1 transcriptional activity in neuroblastoma cells." (PMID 23900341, 2013). "Here, we report a PI3K/AKT2-dependent negative regulation of Gli1 transcriptional activity by AKT2 in neuroblastoma cells." (PMID 23900341, 2013).
neuroblastoma (continued). "Targeting GRP/GRP-R/AKT2 would be advantageous in developing a novel therapeutic option for aggressive and undifferentiated neuroblastomas with a high propensity for metastasis." (PMID 23468863, 2013). "Correspondingly, our murine model demonstrated that silencing AKT2 decreased metastasis to the liver and formation of secondary lesions in comparison to mice injected with control neuroblastoma cells with high endogenous expression of AKT2." (PMID 23468863, 2013). "To determine the functional significance of AKT2-mediated inhibition of Gli1 transcriptional activity in neuroblastoma, we quantified the mRNA levels of RET and MATN2 as downstream targets of Gli1 with or without AKT2 overexpression." (PMID 23900341, 2013). "An inverse relationship between miR-184 and AKT2 mRNA levels was also determined to exist in neuroblastoma cell lines." (PMID 20409325, 2010). "There is still little known about the specific role of each of the three AKT isoforms, however, consistent with our result in neuroblastoma, AKT2 is emerging as one of the more important isoforms with respect to cancer." (PMID 20409325, 2010). "To demonstrate that the increase in cell numbers that occurred following miR-184 knockdown resulted specifically from AKT2 up-regulation, we transfected the pcDNA3-AKT2 plasmid into Kelly neuroblastoma cells." (PMID 20409325, 2010). "In particular, we reported that AKT2 was critical in the regulation of neuroblastoma tumorigenesis." (PMID 31608140, 2019). "Here we hypothesize that targeting AKT2 could block the signal transduction pathways enhanced in chemo- and/or radiation-resistant neuroblastoma cancer stem-like cells." (PMID 31608140, 2019). "Furthermore, we have previously demonstrated that AKT2 plays a key role in regulating tumor metastasis in neuroblastoma." (PMID 31608140, 2019). "miR-122 was reported to play a pivotal role as tumor suppressor by decreasing AKT3 levels, inhibiting cell migration and proliferation and inducing apoptosis, whereas miR-184 was found to be involved in suppressing cell survival and growth by targeting AKT2 in neuroblastoma cells." (PMID 28052756, 2017). "Previous study suggested that hsa-miR-184 suppressed AKT2 expression in neuroblastoma." (PMID 27418134, 2016). "Similarly, silencing of Akt2 in neuroblastoma impaired cellular migration and invasion and decreased liver metastasis." (PMID 26234648, 2015). "Akt2 activity may also promote metastatic potential, as silencing Akt2 reduces anchorage-independent growth, migration, and invasion of neuroblastoma cells in vitro, and decreases their metastatic potential in mice." (PMID 26793165, 2015). "First, AKT2 has been shown to be an miR-184 direct target in neuroblastoma." (PMID 26070602, 2015). "MiR-184 inhibits neuroblastoma cell survival and promotes apoptosis by targeting AKT2." (PMID 24558429, 2014). "Therefore, we conclude that AKT2 has critical oncogenic roles in neuroblastoma cell growth and motility, as well as VEGF secretion in vitro." (PMID 23468863, 2013). "Furthermore, targeting AKT2 decreased VEGF secretion by neuroblastoma cells demonstrating a crucial role for this isoform in tumor cell-mediated angiogenesis." (PMID 23468863, 2013). "Interestingly, silencing AKT2 decreases neuroblastoma cell proliferation, anchorage-independent growth, migration and invasion, and VEGF secretion in vitro." (PMID 23468863, 2013). "Since AKT2 played an important role in the anchorage-independent growth and cell motility of neuroblastoma cells, we speculated that AKT2 might regulate tumor metastasis in vivo." (PMID 23468863, 2013). "Targeting AKT2 signaling and/or activating Gli1 signaling may represent a new therapeutic strategy against undifferentiated neuroblastoma that is often refractory to current treatment regimen." (PMID 23900341, 2013). "Moreover, intrasplenic injection of AKT2 silenced neuroblastoma cells decreased the formation of liver metastases in vivo." (PMID 23468863, 2013).
neuroblastoma (continued). "Therefore, our findings indicate that AKT2 is critically involved in neuroblastoma liver metastasis in vivo." (PMID 23468863, 2013). "Interestingly, silencing GRP-R predominantly reduces AKT2 expression without affecting the expression of AKT1 or AKT3 isoform, thus demonstrating a more critical role of AKT2 in GRP-R-mediated neuroblastoma tumorigenesis." (PMID 23468863, 2013). "Moreover, both migration and invasion of AKT2 stably silenced neuroblastoma cells were decreased by approximately 80% when compared to controls." (PMID 23468863, 2013). "Interestingly, silencing AKT2, but not the AKT1 isoform, significantly increased Gli1 luciferase activity in both human neuroblastoma cell lines examined, thus demonstrating negative regulation of Gli1 by AKT2." (PMID 23900341, 2013). "Overall, a positive regulatory loop might exist between the two oncogenic proteins, AKT2 and N-myc in human neuroblastoma cells, which contributes crucially to tumorigenicity." (PMID 23468863, 2013). "The silencing of AKT2 in cultured neuroblastoma cells resulted in decreased growth and decreased VEGF secretion in vitro, while Akt2-silenced xenografts in nude mice showed fewer liver metastases; therefore, Akt silencing caused the same results as knockout of GRPR in the neuroblastoma cells." (PMID 34539578, 2021). "A detailed characterization based on Akt isoform antibodies and phosphatase experiments in neuroblastoma cells suggested that the peaks with pI 5.06, 5.14, and 5.31 correspond primarily to Akt1, whereas peaks with pI 5.42, and 5.53 correspond to mixed Akt isoforms, most likely Akt1 and Akt2." (PMID 26945062, 2016). "The oncogenic role of AKT2 demonstrated in this study may provide a possible explanation as to why AKT activation has been shown to be a predictor of poor outcome in patients with neuroblastoma." (PMID 23468863, 2013). "Hence, we demonstrate that studying the GRP-R/AKT2/N-myc signaling axis may provide novel insights into the pathobiology of neuroblastoma tumorigenesis." (PMID 23468863, 2013). "Furthermore, silencing AKT2 inhibited migration and invasion of neuroblastoma cells in vitro." (PMID 23468863, 2013). "We found cell proliferation and survival signaling pathways AKT2/mTOR and MAPK were enhanced in cisplatin (CDDP)- and radiation-resistant neuroblastoma cells." (PMID 31608140, 2019). "However, the exact role of AKT2 in neuroblastoma remains unclear." (PMID 23468863, 2013). "This study identifies AKT2 as an important pro-survival gene in neuroblastoma and our results further demonstrate that MYCN indirectly regulates AKT2 through miR-184." (PMID 20409325, 2010). "Decreasing the expression of IGF1R or AKT2 in neuroblastoma cells decreases proliferation, migration, and invasion, validating the IGF1R/PI3 kinase/AKT pathway as a potential therapeutic target in neuroblastoma." (PMID 39001383, 2024). "AKT2 plays an important role in human neuroblastoma cells as a downstream target of GRP/GRP-R and regulates neuroblastoma cell proliferation, anchorage-independent growth, migration and invasion in vitro, implicating AKT2 in multiple aspects of neuroblastoma initiation and progression." (PMID 23468863, 2013). "We treated AKT2 silenced neuroblastoma cells with or without GRP (100 nM) for 2 h after serum-starvation overnight, and IGF-1 (100 nM) was used as positive control." (PMID 23468863, 2013). "Our results indicate that the AKT2 isoform expression levels are critical for neuroblastoma cell survival even in the absence of chemotherapeutic compounds." (PMID 20409325, 2010). "As an inhibitor of AKT2, miR-184 could be of potential benefit in miRNA mediated therapeutics of MYCN amplified neuroblastoma and other forms of cancer." (PMID 20409325, 2010). "Moreover, GRP-R modulates N-myc expression in neuroblastoma cells by AKT2 isoform, but not the AKT1 or AKT3." (PMID 23468863, 2013). "However, the exact role of GRP-R/AKT2 in CDDP-R/Rad-R neuroblastoma cells has not been studied yet." (PMID 31608140, 2019).
neuroblastoma (continued). "In this study, we found that silencing AKT2, but not AKT1 or AKT3 suppresses N-myc expression in neuroblastoma cells." (PMID 23468863, 2013). "Since, GRP-R silencing specifically inhibited the expression of AKT2 isoform, but not AKT1 or AKT3, we can further conclude that GRP-R-mediated regulation of N-myc expression in neuroblastoma cells is AKT2-dependent." (PMID 23468863, 2013). "Our results showed that GRP-R silencing resulted parallel decreased expression of AKT2 and N-myc, however, whether AKT directly effects N-myc expression in neuroblastoma cells has not been determined yet." (PMID 23468863, 2013).
glioblastoma (22 papers, 2010 to 2025). The most malignant astrocytic tumor (WHO grade IV). "Finally, AKT2 also has been reported to be directly implicated in cell migration and invasiveness of glioblastoma." (PMID 20409325, 2010). "When combined with gamitrinib (a mitochondrial homeostasis inhibitor), PI3Ki effectively eliminated PI3K/Akt2/CypD pathway-mediated tumor resistance and significantly induced glioblastoma cell apoptosis." (PMID 35860554, 2022). "In meningioma samples, the expression of Hsa-miR-11181-5p waslower and AKT2 was higher than the normal control, which was the oppositeof glioblastoma." (PMID 34455717, 2021). "Weobserved down-regulation of AKT2 in high-grade glioblastoma tissues, whichconfirmed the role of Hsa-miR-11181 in the AKT2 signalling pathway." (PMID 34455717, 2021). "Therefore, RT-qPCRresults indicated that the AKT2 gene significantly down-regulated in theglioblastoma tumour samples in accordance with high expression levels ofHsa-miR-11181-5p in the glioblastoma tumours." (PMID 34455717, 2021). "Furthermore, increased AKT3 mRNA levels were associated with increased patient survival and lower grade glioblastomas suggesting a more favourable outcome for these patients, whereas AKT1 and AKT2 expression was increased in higher grade tumours." (PMID 28082369, 2017). "LINC00152 modulated glioblastoma (GBM) malignant progression and proneural-mesenchymal transition through the miR-612 dependent AKT2/NF-κB pathway." (PMID 37810780, 2023). "These C. elegans results are similar to those observed in the human glioblastoma cell line, T98G, in which siRNA KD of ROCK1, AKT2, or PKA reduced total aggregate protein by 50–60%." (PMID 35890250, 2022). "Similarly, AKT2 is elevated in U-87 MG and OVISE, indicating possible isoform-specific dependencies in glioblastoma and ovarian clear cell carcinoma." (PMID 41035678, 2025). "In glioblastoma, AKT2 and AKT3 but not AKT1 promote tumor progression, and alterations in the polarity of the PH domain and the regulatory domain were identified as responsible mechanisms for the isoform-specific effect." (PMID 33670586, 2021). "To further characterize gene expression in the Ad-GSCs and Sp-GSCs tumor xenografts, we examined the expression of genes previously defined to be characteristic of the Classical (FGFR3, PDFA, EGFR, AKT-2 and Nestin) and Mesenchymal (CHI3L1, TRADD, NF1, RelB and CASP4) glioblastoma subtypes." (PMID 25955030, 2015). "Down-regulation of AKT2 in U87MG, T98G and TGB cells resulted in areduced apoptosis rate, which confirmed the lower expression of AKT2that we detected in high-grade glioblastoma (data not shown)." (PMID 34455717, 2021).